XG (Xg glycoprotein (Xg blood group))
Synonyms: PBDX
Tractability: Antibody: UniProt places it where antibodies can reach, with high confidence; its Gene Ontology location is reachable by antibodies, with high confidence; UniProt predicts a signal peptide or a membrane-spanning region.
Gene: Protein-coding gene on chromosome X (2,752,040 to 2,816,500, forward strand). Ensembl gene ENSG00000124343.
Subcellular location: Cell membrane
Gene Ontology:
Biological process: homotypic cell-cell adhesion; positive regulation of neutrophil extravasation; T cell extravasation
Cellular component: plasma membrane
Homologues: Orthologues: macaque XG (87% identical), chimpanzee XG (66% identical), dog XG (65% identical), pig XG (63% identical).
Diseases named in the same sentence as XG in open-access papers:
XG is named in the same sentence as 8 diseases in open-access papers, as found by Europe PMC text mining. Sharing a sentence is not in itself a finding about the gene and the disease. The quoted sentences say what the papers report.
Ewing sarcoma (3 papers, 2020 to 2022). A small round cell tumor that lacks morphologic, immunohistochemical, and electron microscopic evidence of neuroectodermal differentiation. "XG, encoding the XG blood group antigen, was associated with lower OS in patients with Ewing’s sarcoma and played a role in metastasis." (PMID 34566519, 2021). "High expression level of XG in Ewing sarcoma cell line could promote tumor migration and invasiveness." (PMID 32296631, 2020).
breast carcinoma (2 papers, 2024). "Focusing on individual genes, our multivariate COX regression analysis identified ZMAT3 and XG as independent prognostic risk factors for breast cancer, with ZMAT3 having the highest HR value." (PMID 39664194, 2024). "Kaplan-Meier curves show that SDC1, NACAD, ZMAT3, CCND2, XG and SGCE are associated with prognosis in breast cancer patients." (PMID 39664194, 2024). "Initially, univariate Cox regression analysis revealed that 12 genes were associated with the prognosis of breast cancer, followed by LASSO analysis to derive a prognostic signature composed of 8 genes, including CERCAM, EMP1, SDC1, PRKG1, XG, TNN, WLS, and PDLIM4." (PMID 38728370, 2024). "Multivariate Cox regression analyses in the TCGA dataset showed that XG and ZMAT3 were independent prognostic risk factors for breast cancer, and ZMAT3 had higher HR values, suggesting that it may be a key gene influencing the prognosis of breast cancer." (PMID 39664194, 2024).
atherosclerosis (1 paper, 2022). A disease characterized by the build-up of fatty material and calcium deposition in the arterial wall resulting in partial or complete occlusion of the arterial lumen. "However, the role played by XG in atherosclerosis remains uncharacterized." (PMID 36345357, 2022).
autism spectrum disorder (1 paper, 2016). A spectrum of developmental disorders that includes autism, and Asperger syndrome. "Both genes, XG and NLGN4X, are related to autism spectrum disorders that are also appropriately distributed among these populations." (PMID 27042214, 2016).
tumor (2 papers, 2020 to 2025). "Notably, the reduced expression of XPNPEP2 and XG implies heightened vascular permeability and an inflammatory microenvironment, which may further facilitate tumor progression." (PMID 40950184, 2025).
brain diseases (1 paper, 2025). "While the roles of PAEP, CCN5, and XG in brain diseases are not yet fully understood, our study identifies significant associations between these proteins and brain structure, offering a valuable basis for future studies." (PMID 40456753, 2025).
cardiovascular diseases (1 paper, 2022). "TCF21, CDH19, XG, and NNAT might serve as feature genes for CAD, providing new insights for future research on the pathogenesis of cardiovascular diseases." (PMID 36345357, 2022). "In addition, the four feature genes identified (TCF21, CDH19, XG, and NNAT) might serve as feature genes for CAD, bringing new insights into the pathogenesis of cardiovascular diseases." (PMID 36345357, 2022).
XG also shares sentences with these, for which no sentence is quoted: infection (1 paper).